EPO (erythropoietin)
Diseases named in the same sentence as EPO in open-access papers (continued):
Sharing a sentence is not in itself a finding about the gene and the disease.
injury (30 papers, 2006 to 2026). Damage inflicted on the body as the direct or indirect result of an external force, with or without disruption of structural continuity. "A recent study examined the associations between the management of acute head injury patients with a restrictive versus a liberal transfusion threshold and the administration of erythropoietin with neurological outcomes at 6 months as the primary endpoint." (PMID 26869986, 2016). "This study investigated whether EPO concentrations in the first month of life were driven by individual perinatal risk factors and were associated with subsequent outcomes and brain injury as assessed by MRI prior to NICU discharge." (PMID 34077474, 2021). "The purpose of the present study was to investigate the effect of erythropoietin (EPO) on lung ischemia-reperfusion injury (LIRI)." (PMID 38560469, 2024). "Erythropoietin (EPO) is clinically used in neonatology to mitigate acute brain injury, and to stimulate neuronal maturation." (PMID 33495244, 2021). "Given that the injured cortex is a toxic microenvironment we also administered EPO, due to its reported neuroprotective effects following brain injury and its enhancement of neurogenesis in models of neural damage." (PMID 27071013, 2016). "The results of our study are in concordance with the most recent study in acute head injury patients; however, that study was compromised by the concomitant use of erythropoietin and a small sample size." (PMID 26869986, 2016). "In conclusion, following traumatic brain injury, EPO significantly decreased the number of apoptotic cells, the expression of MCP-1, the infiltration of CD68+ cells as well as brain edema to protect the brain." (PMID 23226759, 2012). "This study aimed to explore the effect of erythropoietin (EPO) on brain tissue after traumatic brain injury in rats." (PMID 23226759, 2012). "This increase in EPO, a well-known response to hypoxia, suggests that EPO may play a role in the mobilization of these cells following neonatal severe brain injury and, consequently, in the regeneration effort of the damaged tissue and its vasculature." (PMID 40149963, 2025). "EPO has known neuroprotective effects and showed promising results in a stage II clinical trial, where infants treated with both EPO and therapeutic hypothermia presented with lesser MRI-assessed brain injury and improved motor function in the short term." (PMID 38607070, 2024). "It was found that EPO can reduce hypoxic-ischemic brain damage by reducing the expression of Fas and FasL, and the optimal therapeutic time window is 6–24 hours after brain injury." (PMID 35611764, 2022). "Endogenous Erythropoietin (EPO) concentrations in premature infants may both be a biomarker for hypoxic stress and have an influence on the response to brain injury." (PMID 34077474, 2021). "n in vitro or vivo models, EPO has been effective in improving functional outcomes after the experimental induction of traumatic brain injury and spinal cord injury, limiting neuronal damage-associated epilepsy and reducing chemotherapy-induced peripheral neurotoxicity." (PMID 29385149, 2018). "Recent data show that ARA290, a derivative of EPO, exert a strong anti-inflammatory effect by suppression of the spinal microglia response in a mouse model of neuropathic pain induced by spared nerve injury." (PMID 25422898, 2014). "However, only early application of hypothermia or administration of recombinant human erythropoietin has demonstrated clinical effectiveness in full-term infants suffering from brain injury." (PMID 25211332, 2014). "The majority of the pre-clinical research in animal models evaluating the effectiveness of EPO in brain injury utilized a dose of 5000 U/kg, which was tested at various time-points ranging from a pretreatment up to 9 h post-injury, with earlier administration resulting in greater benefits." (PMID 24151467, 2013).
injury (continued). "Beneficial therapeutic effects of exogenously administered whole molecule EPO have been described in several animal models of neurologic injury, including occlusive cerebral vascular disease, acute brain trauma, epilepsy, as well as in both autoimmune arthritis and EAE." (PMID 18382691, 2008). "Erythropoietin (EPO) improves neuronal mitochondrial function and cognition in adults after brain injury and in those afflicted by psychiatric disorders." (PMID 34354241, 2021). "Importantly, EPO administration 1 hour after injury was sufficient to reduce IL-1β to sham levels, highlighting EPO’s ability to modulate neuroinflammation early and robustly after diffuse TBI, as reported in models of focal brain injury." (PMID 24344874, 2013).
thrombosis (30 papers, 2009 to 2026). "Systemic EPO administration always increases the hematocrit value of the subjects and further elevates the risk of thrombosis." (PMID 30744451, 2019). "Erythropoietin-producing uterine myoma can cause various complications such as arterial or venous thrombosis and bleeding." (PMID 32025892, 2018). "One limitation of this approach is that high doses of EPO are associated with an increased risk of thrombosis in clinical settings." (PMID 29201007, 2017). "In addition, supportive therapeutic agents such as erythropoietin, high dose corticosteroids as antiemetics, and granulocyte colony-stimulating factor (G-CSF) may increase the risk of vascular thrombosis." (PMID 31852092, 2019). "The timing of EPO administration was immediately after induced coronary thrombosis in animal studies; EPO doses ranged from 2,500 to 5,000 IU per kg in rats versus 430-860 IU per kg in humans." (PMID 35812547, 2022). "In a small-scale, double-blind, placebo-controlled study, EPO increases the incidence of thrombosis by 15% among healthy male volunteers." (PMID 33213494, 2020). "Generally, the systemic administration of EPO would result in the unwanted hematocrit elevation which further exacerbates angiogenesis and thrombosis." (PMID 28891332, 2017). "However, much evidence has confirmed that EPO treatment can induce systemic adverse effects in the clinical fields, including coronary stent thrombosis and deep vein thrombosis." (PMID 42196412, 2026). "Furthermore, thromboembolic events, such as deep vein thrombosis (DVT) and pulmonary embolism, have been linked to EPO medication." (PMID 37697015, 2023). "A systematic review identified multiple putative beneficial brain targets of EPO treatment, e.g., modulation of inflammation, neuroprotection, neurotransmission regulation, effects on BBB permeability, but the use of EPO can be limited by adverse effects such as thrombosis and cancer." (PMID 24550848, 2014). "A total of three studies involving 739 patients showed that EPO did not increase the incidence of deep vein thrombosis in patients with TBI." (PMID 36582613, 2022). "None of the known side effects of EPO including increase in blood pressure, and venous thrombosis due to excessive erythropoeisis, were observed during the 7 days follow-up." (PMID 19630971, 2009).
depression (29 papers, 2010 to 2025). "The specificity of EPO’s action on the left hippocampus is interesting as previous evidence in major depression shows larger volume loss in the left hippocampus." (PMID 34552490, 2021). "There are also recent studies investigating that EPO levels may be associated with suicidality in patients with depression." (PMID 38995319, 2024). "Focusing on erythropoietin may help us understand the pathogenic mechanisms of depression and the molecular basis of its treatment." (PMID 27164096, 2016). "EPO treatment has been investigated in human studies in psychiatric disorders such as treatment-resistant depression, bipolar disorder, and schizophrenia and in an animal model of autism spectrum disorder." (PMID 38995319, 2024). "A double-blinded randomized clinical trial in a treatment-resistant depression population using EPO reported an improvement in depression scores and cognition." (PMID 37511274, 2023). "Extending our analysis to reconstruct the GRNs, we observe that the regulons that are critical for long-term memory, combatting depression, improving cognition, and synaptic plasticity are relatively enriched in the newly formed neurons of EPO samples." (PMID 37604818, 2023). "Mechanistically distinct compounds, such as EPO, which directly increases cellular resilience and plasticity hold great promise as novel faster acting treatments of depression." (PMID 30310078, 2018). "Patients with unipolar or bipolar disorder with current moderate to severe depression referred to ECT (N = 52) are randomized to receive four high-dose infusions of EPO (40,000 IU/ml) or placebo (saline)." (PMID 29673379, 2018). "For this review, we present evidence that EPO-induced signaling pathways are involved in antidepressant activity or regression of depression, and describe the potential of EPO as a novel antidepressant." (PMID 27164096, 2016). "Seven patients were given erythropoietin to improve hemoglobin, and six were treated for mild depression." (PMID 24358041, 2013). "We note that a recent study reported on better facial recognition performance in patients with major depression following high-dose EPO application, supporting social cognition as another selective target of EPO effects across species." (PMID 21527022, 2011). "Further, it has been seen that erythropoietin impacts neuroplasticity and could be used to treat depression in the future." (PMID 36986674, 2023). "Clinical studies on EPO in chronic brain diseases (schizophrenia, multiple sclerosis, major depression and bipolar disorder) with extended treatment using high-dose EPO over many weeks showed consistently advantageous effects on cognition, motor function, and even reduction of brain matter loss." (PMID 32546125, 2020). "Miskowiak et al23 examined objective baseline verbal memory dysfunction related to cognitive change in an RCT of erythropoietin infusion for moderately depressed patients with unipolar depression and patients with bipolar disorder in partial remission (n = 79)." (PMID 33121560, 2020). "In a study on EPO as a treatment option for memory impairment in neuropsychiatric diseases, recombinant human EPO could consistently improve memory and cognition in patients with multiple sclerosis, schizophrenia, major depression, and bipolar disorder." (PMID 32066684, 2020). "A complex relationship between EPO, GSK3β, the hippocampus and depression may exist, in part, through nitric oxide (NO)-related pathways." (PMID 30310078, 2018). "In this review, we highlight evidence collectively suggesting that inhibition of GSK3β acts as a multi-potent molecular mechanism that may mediate multi-potent effects of EPO on hippocampal volume changes in depression." (PMID 30310078, 2018).
depression (continued). "Randomized controlled clinical studies suggest that 8–12 weeks of systemically administered high-dose (40,000–48,000 IU) EPO improves attention, memory, and executive functions in patients with treatment-resistant depression (TRD), bipolar disorder (BD), multiple sclerosis, or schizophrenia." (PMID 29673379, 2018). "Given preliminary evidence for the beneficial effects of EPO on depression-relevant outcomes, a secondary hypothesis is that add-on EPO treatment will produce greater, more sustained mood improvement than ECT treatment alone." (PMID 29673379, 2018). "Thus, the influence of erythropoietin on the downstream pathways known to be involved in the treatment of depression makes the erythropoietin-related pathway an attractive target for the development of new therapeutic approaches." (PMID 27164096, 2016). "We will also introduce the possibility that certain immune cytokines that have trophic properties [e.g., erythropoietin (EPO)] might contribute novel antidepressant properties consistent with a neuroplastic view of depression." (PMID 24312008, 2013). "As alluded to earlier, MIF and EPO might be related to depressive disorders, although the available data are admittedly limited." (PMID 23675319, 2013). "Like MIF, there is reason to believe that EPO could serve in a therapeutic capacity in the treatment of depressive disorders." (PMID 23675319, 2013). "Indeed, they reported that HIF-1 may produce beneficial effects on depression, as it targets genes that have been shown to elicit antidepressant effects in animal models (erythropoietin (EPO) and vascular endothelial growth factor (VEGF) genes." (PMID 34790666, 2021). "The present EPO study is the first clinical trial investigating whether repeated administration of Epo is able to improve mood and reverse neurocognitive dysfunction in patients with treatment resistant depression or bipolar illness in remission." (PMID 20942940, 2010). "The presence of CAD or use of EPO were frequently observed in dialysis patients with IBS, and psychopathologies in depression, somatization, and additional sub-parameters were also higher in these patients." (PMID 35110100, 2021). "Based on the protective effect of higher genetically determined CSF EPO levels on WMH volume, potential repositioning of EPO analogs crossing the BBB and studied in phase II clinical trials for other indications (depression, neuropathy) is a compelling example." (PMID 41266628, 2025). "In a randomized, double-blind, placebo-controlled study of treatment-resistant depression, EPO did not improve Hamilton Depression Rating Scale-17 (HDRS-17) scores after an 8-weeks dosing regimen." (PMID 34552490, 2021). "If EPO is found to alleviate cognitive side effects of ECT, this could have important implications for future treatment strategies for severe depression and for the scientific understanding of the neurobiological etiology of ECT-related cognitive decline in patients treated with ECT." (PMID 29673379, 2018). "If EPO is found to reduce the cognitive side effects of ECT, this could have important implications for future treatment strategies for depression and for the scientific understanding of the neurobiological etiology of cognitive dysfunction in patients treated with ECT." (PMID 29673379, 2018). "However, there was significant improvement in the Beck’s Depression Inventory-21 (BDI-21), World Health Organization Quality of Life-BREF (WHOQOL-BREF) score and mood-independent verbal memory, that were maintained for at least 6 weeks after the last dose of EPO." (PMID 34552490, 2021). "It was observed that a single dose of erythropoietin (Eprex; 40,000IU) could improve cognitive functioning and reduce the neurocognitive processing involved in negative emotional information in normal versus people with depression in a way that is similar to antidepressants’ effects." (PMID 36986674, 2023).
depression (continued). "These growth factors, to varying degrees, have been related to depressive disorders, although in the case of VEGF, MIF, and EPO it does not seem as if they systematically vary in depressed patients." (PMID 23675319, 2013).
myeloproliferative neoplasm (27 papers, 2011 to 2026). A clonal hematopoietic stem cell disorder, characterized by proliferation in the bone marrow of one or more of the myeloid (i.e., granulocytic, erythroid, megakaryocytic, and mast cell) lineages. "Clinicians should also ascertain a history of antecedent MDS, myeloproliferative neoplasm, and erythropoietin level, as this information impacts the diagnostic classification." (PMID 38892446, 2024). "The JAK2 V617F mutation, which is associated with myeloproliferative disorders and EPO hypersensitivity, was identified exclusively in blasts of TgSpi1FA+/+ mice, including #445 and #451, with VAF values of 28 and 18%, respectively." (PMID 37573408, 2023). "Additional testing, including PCR or FISH techniques for bcr-abl, JAK-2 mutational testing, erythropoietin levels, and bone marrow examination with cytogenetics, must be warranted for patients suspected of having a myeloproliferative neoplasm." (PMID 25431700, 2014). "Here, we investigated EPO and thrombopoietin (TPO) induced SOCE and PLCγ1 activation in hematopoietic cells exhibiting activating mutations in JAK2 and CALR which are disease-initiating events in myeloproliferative neoplasms (MPNs)." (PMID 38509561, 2024). "Renal echo ultrasound and further imaging studies may be arranged to exclude the possibility of hydronephrosis if genetic mutations or evidence of myeloproliferative neoplasm are not found, especially in patients with normal or low EPO levels." (PMID 39767963, 2024). "In this case, the index patient was also found to have a persistently high hemoglobin level with suppressed erythropoietin level despite a negative panel for mutations of myeloproliferative disease and absent bone marrow biopsy evidence of clonal red cell disorder." (PMID 39867034, 2024). "Polycythemia vera (PV) is classified as a myeloproliferative neoplasm characterized by the autonomous overproduction of erythrocytes by hematopoietic stem cells (HSC), occurring independently of erythropoietin (EPO) stimulation." (PMID 39682300, 2024). "VFEpoR mice also showed increased RDW and lower serum EPO level, similar to patients with JAK2VF myeloproliferative neoplasm." (PMID 35587375, 2022). "Furthermore, it has been reported that the JAK2/STAT3 pathway participates in the protective effect of erythropoietin (EPO) in subarachnoid hemorrhage (SAH); also, JAK2 and telomerase have a combination effect in the treatment of myeloproliferative neoplasms (MPNs)." (PMID 34585328, 2021).
uremia (27 papers, 2011 to 2025). A clinical syndrome associated with the retention of renal waste products or uremic toxins in the blood. "Indeed, hormonal abnormalities (decrease of free and total testosterone levels, hyperprolactinemia, decline of erythropoietin levels), neuropathy associated with uremia, endothelial dysfunction, psychological factors and drugs (first of all diuretics) occur in these patients." (PMID 32422943, 2020). "One patient was treated with erythropoietin, ferrous sulfate, and bicarbonate for metabolic acidosis from obstructive nephropathy leading to uremia." (PMID 40710916, 2025). "Renal anemia is a multifactorial process caused by relative erythropoietin (EPO) deficiency, uremia-induced inhibitors of erythropoiesis, shortened erythrocyte survival, and disordered iron homeostasis." (PMID 37430374, 2023). "Renal anemia is caused by multiple factors, including primarily decreased erythropoietin (EPO) production as the main factor, as well as hematopoietic suppression due to uremia, shortened erythrocyte survival, and abnormal iron metabolism." (PMID 36769359, 2023). "On the other hand, uremia from pre-existing renal injury might interfere with EPOR and the immunomodulatory functions of EPO along with uremia-induced dysfunctions in other organs." (PMID 34831360, 2021). "However, as CKD progresses, the impact of erythropoietin produced by renal cysts may diminish due to uremia, which suppresses the bone marrow’s response to erythropoietin, resulting in decreased hemoglobin levels." (PMID 38427307, 2024). "Erythropoietin (EPO) was originally used for treating anemic patients of various etiologies, especially for patients with uremia." (PMID 21269484, 2011). "This lack of increase in renal and BM HIF2α in uremia naturally leads to a lack of increase in EPO levels." (PMID 29738538, 2018).